MSH6 (mutS homolog 6)
Diseases named in the same sentence as MSH6 in open-access papers (continued):
Sharing a sentence is not in itself a finding about the gene and the disease.
meningioma (2 papers, 2021 to 2023). A generally slow growing tumor attached to the dura mater.
neuroblastoma (2 papers, 2023). Neuroblastoma (NB) is the most common solid, extracranial childhood tumor.
ovarian clear cell cancer (2 papers, 2022). An invasive malignant neoplasm that arises from the ovary and is characterized by a predominance of clear and hobnail malignant epithelial cells. "Only case 403, an ovarian clear cell carcinoma, presented dMMR with a concrete pattern of expression loss in MSH6." (PMID 36010253, 2022). "Ovarian clear cell carcinoma (OCCC) (n = 28) and endometrial clear cell carcinoma (ECCC) (n = 28) samples were evaluated for PD-L1 (in tumoral and peri-tumoral inflammatory cells), MSH6 and PMS2 expression by immunohistochemistry (IHC) study." (PMID 36581850, 2022).
pancreas carcinoma (2 papers, 2023). "The other patient was diagnosed with a Lynch associated pancreatic carcinoma and was enrolled because of isolated loss of MSH6 by IHC." (PMID 36870947, 2023).
renal carcinoma (2 papers, 2019 to 2023). A carcinoma arising from the epithelium of the renal parenchyma or the renal pelvis.
tuberous sclerosis (2 papers, 2016 to 2025). Hereditary disease characterized by seizures, intellectual disability, developmental delay, and skin and ocular lesions.
undifferentiated pleomorphic sarcoma (2 papers, 2022). An undifferentiated soft tissue sarcoma characterized by the presence of a pleomorphic malignant cellular infiltrate. "Two patients had alterations in both MLH1 and MSH6 (both undifferentiated pleomorphic sarcoma)." (PMID 36741731, 2022).
upper tract urothelial carcinoma (2 papers, 2021 to 2022).
acute lymphoblastic leukemia (1 paper, 2023). Leukemia with an acute onset, characterized by the presence of lymphoblasts in the bone marrow and the peripheral blood. "Two of the genes associated with the MMR pathway, MSH6 and SETD2, were among the genes found to be frequently mutated in relapsed or therapy resistant ETV6/RUNX1 acute lymphoblastic leukemia (ALL)." (PMID 36672189, 2023).
adrenocortical carcinoma (1 paper, 2021). "MSH6 was highly expressed in most cancers, and the high expression of MSH6 was associated with poor overall survival prognosis of patients with multiple cancers, such as adrenocortical carcinoma." (PMID 34941572, 2021).
autosomal dominant polycystic kidney disease (1 paper, 2025). Autosomal dominant form of polycystic kidney disease. "WES revealed additional genetic diagnoses, including hereditary hemochromatosis-associated variants (n = 5), familial Mediterranean fever (n = 4), homozygous MSH6 mutation-associated hereditary cancer predisposition (n = 2), and autosomal dominant polycystic kidney disease (ADPKD) (n = 2)." (PMID 41282474, 2025).
biliary tract cancer (1 paper, 2017). "Besides the mutation in MSH6, we identified 3 more mutations affecting genes described in cancer, but only rarely reported in biliary tract cancer (≤ 2%; SRC, MSN, PTPRC)." (PMID 28146430, 2017).
bone cancer (1 paper, 2023). A primary or metastatic malignant neoplasm affecting the bone or articular cartilage. "Two further cases of bone cancer were cited in patients with MSH6 pathogenic variant." (PMID 37370996, 2023).
bone metastasis (1 paper, 2025). Transfer of a neoplasm from its primary site to bones. "Bone metastasis was correlated with lost MSH6 marker (p = 0.025)." (PMID 39762286, 2025).
bone sarcoma (1 paper, 2022). A sarcoma that arises from the bone.
Branchioma (1 paper, 2023). A tumor derived from branchial epithelium or branchial rests. "We herein expand on the spectrum of molecular findings in branchioma, in which we detected 5 pathogenic/likely pathogenic gene mutations, particularly two MSH6 mutations, two PTEN mutations, and one KRAS alteration, indicating molecular heterogeneity in branchioma." (PMID 37401932, 2023).
Cervical tumor (1 paper, 2025).
colon adenoma (1 paper, 2017). An adenoma that arises from the colon. "MSI analysis showed an MSI-low (L); IHC showed the absence of MSH6 protein in tumor tissue, but segregation analysis showed that the variant was not present in the sister (II:4) of the index case, who also developed two colon adenomas, one of which with severe dysphasia." (PMID 28481244, 2017).
colonic adenomatous polyps (1 paper, 2023).
common variable immunodeficiency (1 paper, 2018).
cutaneous squamous cell carcinoma (1 paper, 2021).
deficient (1 paper, 2022). "Approximately 3% of ECs are caused by germline mutations in the MMR genes such as MLH1/2, MSH6, and PMS2 and are termed MMR-deficient (MMR-D) tumors." (PMID 35965548, 2022).
endometrial adenocarcinoma (1 paper, 2018).
esophageal SCC (1 paper, 2017). "The ATF suppressed MSH6 mRNA and protein expression in EBC2 cells, TE4 cells and TE10 cells suggesting that these genes might be downstream genes of SOX2 in lung and esophageal SCC." (PMID 29262545, 2017).
Friedreich ataxia (1 paper, 2014). An inherited condition that affects the nervous system and causes movement problems. "However, while MSH6 has been shown to be important for expansion in Friedreich ataxia (FRDA) induced pluripotent stem cells, in mouse models of other repeat expansion diseases, it is MSH3 that is important." (PMID 25101111, 2014).
gastric leiomyoma (1 paper, 2014). A rare benign smooth muscle neoplasm arising from the wall of the stomach. "The genes found methylated in the gastric leiomyoma play different functions in the cell: MLH1, MSH3, MGMT, and MSH6 participate in DNA repair functions whereas APC gene participates in cell proliferation." (PMID 25544907, 2014).
gliosarcoma (1 paper, 2021). A rare histological variant of glioblastoma (WHO grade IV) characterized by a biphasic tissue pattern with alternating areas displaying glial and mesenchymal differentiation (WHO). "Strikingly, we found a hypermutated phenotype in our patient’s specimen, including mutations in MMR genes, MSH3 and MSH6, which previously have not been associated with gliosarcoma pathology." (PMID 33580181, 2021).
granulosa cell tumor (1 paper, 2017). A slow-growing, malignant tumor, characterize by the presence of granulosa-like cells and Call-Exner bodies, that is almost always found in the ovary.
hyper-IgM syndrome (1 paper, 2018). A primary immune deficiency disorder characterized by defective CD40 signaling; via B cells affecting class switch recombination (CSR) and somatic hypermutation. "For example, deficiency of UNG or Msh6 results in primary human immunodeficiency presenting as a class-switching defect, also called Hyper-IgM syndrome." (PMID 29389970, 2018).
intestinal type adenocarcinoma (1 paper, 2025). An adenocarcinoma arising from epithelium which has undergone intestinal metaplasia.
intraepithelial neoplasia (1 paper, 2022). A precancerous neoplastic process that affects the squamous, glandular, or transitional cell epithelium without evidence of invasion.
Legius syndrome (1 paper, 2022). Legius syndrome, also known as NF1-like syndrome, is a rare, genetic skin pigmentation disorder characterized by multiple cafC)-au-lait macules with or without axillary or inguinal freckling.
marginal zone lymphoma (1 paper, 2024). A usually indolent mature B-cell lymphoma, arising from the marginal zone of lymphoid tissues. "CGP additionally resulted in genetic counseling consultation for three patients: one patient with CLL who was found to have a BRCA2 mutation, one patient with CLL who was found to have an MSH6 mutation, and one patient with marginal zone lymphoma who was found to have a VHL mutation." (PMID 39449302, 2024).
Metrorrhagia (1 paper, 2023). Bleeding at irregular intervals. "A 65-year-old women coming from a family with LS (MSH6 mutation) was reported with post-menopausal metrorrhagia due to ACC as the first manifestation of LS." (PMID 37296718, 2023).
mismatch repair cancer syndrome (1 paper, 2024). "Compound heterozygosity for NM_000179.3:c.3226C>T in the MSH6 gene has been reported in the literature in three unrelated cases and two sisters with constitutional mismatch repair cancer syndrome." (PMID 39436407, 2024).
mixed cell type cancer (1 paper, 2022). A cell type cancer that has_material_basis_in abnormally proliferating cells derived_from two germinal layers of tissue. "The non-endometrioid histology cancer types found in patients with MSH6 mutations included serous (n = 1), neuroendocrine (n = 1), dedifferentiated (n = 1), and mixed type (n = 1) cancers, whereas only one case of mixed cell type cancer was found among patients with PMS2 mutations." (PMID 35884469, 2022).
mucosal melanoma (1 paper, 2023). A melanoma that arises from a mucosal site. "Roncati (2018) reported a patient with mucosal melanoma and MMR-deficiency for MSH6 who experienced long-term disease control under PD-1 blockade with pembrolizumab." (PMID 35419731, 2023).
multinodular goiter (1 paper, 2024). Nodular goiter characterized by more than one discrete tissue mass.
myotonic dystrophy type 1 (1 paper, 2024). Steinert disease, also known as myotonic dystrophy type 1, is a muscle disease characterized by myotonia and by multiorgan damage that combines various degrees of muscle weakness, arrhythmia and/or cardiac conduction disorders, cataract, endocrine damage, sleep disorders and baldness. "In a mouse models of myotonic dystrophy type 1 (DM1), loss of MSH6 led to increased expansion in non-neuronal tissue." (PMID 38749429, 2024).
myxofibrosarcoma (1 paper, 2004). A malignant fibroblastic neoplasm arising from the soft tissue.
pancreatic ductal adenocarcinoma (1 paper, 2020). An infiltrating adenocarcinoma that arises from the epithelial cells of the pancreas.
pancreatitis (1 paper, 2015). Inflammation of the pancreas. "The DEGs, including Cdc6, Mcm6, Msh6 and Wdr1 are closely associated with the regulation of caerulein-induced pancreatitis." (PMID 25975747, 2015). "In the current study, Cdc6 and Msh6 were identified as DEGs in wild type and Mist1KO mice, further indicating the importance of these two genes in caerulein-induced pancreatitis." (PMID 25975747, 2015). "Msh6 and Wdr1 may be involved in the regulation of pancreatitis through DNA mismatch repair and acinar cells, respectively." (PMID 25975747, 2015). "Although the involvement of Msh6 in pancreatitis has not been clearly defined, it is considered that Msh6 is involved in the regulation of pancreatitis via DNA mismatch repair." (PMID 25975747, 2015).
perihilar cholangiocarcinoma (1 paper, 2019).
Pilomatricoma (1 paper, 2020).
prostate intraepithelial neoplasia (1 paper, 2021). A neoplastic proliferation of the epithelial cells that line the acini and the ducts of the prostate gland. "Additionally, three men (one MLH1 carrier, one MLH1 non-carrier control, and one MSH6 carrier) had either atypical small acinar proliferation or high-grade prostate intraepithelial neoplasia." (PMID 34678156, 2021).
protein (1 paper, 2019).
pseudomyxoma peritonei (1 paper, 2018). An appendix cancer that is characterized by progressive accumulation of mucus-secreting tumor cells within the abdomen and pelvis. "In two patients, the transposed ovaries (both ovarian survival at the time of surgery) were removed after, respectively, 2 (due to pseudomyxoma peritonei) and 45 months (preventive surgery because of MSH-6 mutation)." (PMID 30218184, 2018).
small cell carcinoma (1 paper, 2022). A neuroendocrine carcinoma composed of small malignant cells which are often said to resemble "oat cells" under the microscope.
thymic tumors (1 paper, 2016). "We initially also included Msh6-/- mice, but they did not tolerate ENU treatment even at a reduced dose, as they developed thymic tumors with enlarged lymph nodes and spleens (data not shown)." (PMID 27441645, 2016).
thyroid disease (1 paper, 2024).
thyroid nodule (1 paper, 2024). A small circumscribed mass in the THYROID GLAND that can be of neoplastic growth or non-neoplastic abnormality. "A high prevalence of thyroid nodules is found in patients with LS, especially in MSH6 carrier patients." (PMID 39062638, 2024).
undifferentiated thyroid carcinoma (1 paper, 2015).
ureteral tumour (1 paper, 2024). "The patient also had pancreatic and renal tumors, and two ureteric tumors without MSI but with a loss of MSH6 expression by immunohistochemistry (IHC) on ureteral tumour cells and weak expression on tumour-adjacent cells." (PMID 39031223, 2024).
uterine serous adenocarcinoma (1 paper, 2018). "The first case involved patient 5, who had a history of uterine serous adenocarcinoma and a germline VUS in MSH6 (p.R976C) that was also detected in her mother." (PMID 29755653, 2018).